SIK2 (salt inducible kinase 2)
Diseases named in the same sentence as SIK2 in open-access papers (continued):
Sharing a sentence is not in itself a finding about the gene and the disease.
pulmonary fibrosis (continued). "However, the role of SIK2 on pulmonary fibrosis remains unclear, and whether SIK2 inhibitor can attenuate pulmonary fibrosis is unknown." (PMID 35410283, 2022). "Furthermore, the anti-fibrotic activity of ARN-3236 was blocked by the CREB inhibitor 666-15, indicating that inactivation of SIK2 might alleviate pulmonary fibrosis through CRTC2-mediated CREB pathway." (PMID 35410283, 2022). "Interestingly, Dasatinib, a dual tyrosine kinase/SIK2 inhibitor, has been identified as an anti-fibrotic agent in mice with pulmonary fibrosis, suggesting that SIK2 inhibition might be an effective anti-fibrosis therapeutic approach." (PMID 35410283, 2022). "Supporting a role for SIK2, a recent study has shown that a compound developed as an SIK inhibitor, ARN-3236, is able to attenuate bleomycin-induced lung fibrosis." (PMID 36309093, 2022). "Inhibition of SIK2 by ARN-3236 prevented the fibroblasts differentiation and extracellular matrix expression in HFLs and attenuated bleomycin-induced pulmonary fibrosis in mice." (PMID 35410283, 2022). "Additionally, it demonstrates the efficacy and preliminary safety of selectively targeting SIK2 using the inhibitor YKL-06-062 and the repurposed agent fostamatinib in mitigating pulmonary fibrosis in vivo." (PMID 40868174, 2025). "In contrast to this, SIK2 appears to be the predominant isoform regulating lung fibrosis, although a contribution from SIK3 cannot be ruled out." (PMID 36309093, 2022). "There is downregulation of Sik2 from the IGF pathway, which is well known to have a role in aging, and of Tgfbr3, from the TGFβ pathway, which is important for lung development and pathogenesis of pulmonary fibrosis." (PMID 32591591, 2020). "Together, this suggests that during bleomycin-induced lung fibrosis, the main effects of SIK2 inhibition may not be due to its anti-inflammatory role in macrophages, and that it could potentially be acting via a novel substrate." (PMID 36309093, 2022).
clear cell renal cell carcinoma (5 papers, 2022 to 2025). "Fto demethylates salt-inducible kinase 2 (Sik2) mRNA, reducing its binding to Igf2bp2 and promoting degradation, which inhibits autophagy and facilitates clear cell renal cell carcinoma proliferation and metastasis." (PMID 41208876, 2025). "For instance, in clear cell renal cell carcinoma (ccRCC), IGF2BP2 stabilizes salt-inducible kinase 2 (SIK2) mRNA via FTO-mediated m6A modification, enhancing autophagic flux and reducing ccRCC growth and metastasis." (PMID 39596216, 2024). "In clear cell renal cell carcinoma (ccRCC), IGF2BP2 stabilizes salt inducible kinase 2 (SIK2) mRNA to enhance autophagic flux via the FTO-mediated m6A modification, diminishing the ccRCC growth and metastasis." (PMID 37554271, 2023). "In clear cell renal cell carcinoma, SIK2 downregulation promotes tumor progression by inhibiting autophagy, depending on FTO/IGF2BP2-m6A axis-mediated SIK2 mRNA stabilization." (PMID 37280679, 2023).
gastric cancer (5 papers, 2021 to 2025). A primary or metastatic malignant neoplasm involving the stomach. "Salt‐inducible kinase 2 (SIK2) functions as a tumor suppressor in gastric cancer (GC)." (PMID 33128264, 2021). "However, the involvement of SIK2 in gastric tumorigenesis and the functional linkage with gastric cancer (GC) progression remain to be defined." (PMID 33128264, 2021).
osteoporosis (5 papers, 2017 to 2026). A condition of reduced bone mass, with decreased cortical thickness and a decrease in the number and size of the trabeculae of cancellous bone (but normal chemical composition), resulting in increased fracture incidence. "These reassuring results suggest a favorable initial safety profile associated with whole body SIK2/3 gene deletion, and further support the idea of this target combination for osteoporosis drug development." (PMID 34160349, 2021). "These SIK2 inhibitors may replace anti-sclerostin antibodies in the treatment of osteoporosis in the future." (PMID 35563281, 2022). "Therefore, direct small molecule SIK2/SIK3 inhibitors may represent a strategy to mimic PTH actions to treat different forms of osteoporosis." (PMID 41908158, 2026). "The role of SIK2 and 3 in bone formation has been recently investigated in osteocytes in which it has been demonstrated that SIK inhibitors in vitro can mimic the effect of parathyroid hormone (PTH), the only approved osteoporosis treatment that stimulates new bone formation." (PMID 28973003, 2017). "Dual targeting of SIK2/3 and CSF1R induces bone formation without concomitantly increasing bone resorption and thereby may overcome limitations of most current anabolic osteoporosis therapies." (PMID 34160349, 2021).
brain ischemia (4 papers, 2011 to 2022). Diminished or absent blood supply to the brain caused by obstruction (thrombosis or embolism) of an artery resulting in neurologic damage. "Previous studies have shown that Salt-induced kinase-2(SIK2) is involved in the regulation of various energy-metabolism-related reactions, and it also can regulate angiogenesis after cerebral ischemia-reperfusion." (PMID 35586047, 2022). "It is concluded that SIK2 can ameliorate neuronal injury and promote the energy metabolism by regulating the mTOR pathway during cerebral ischemia-reperfusion, and this process is related to mitochondrial autophagy." (PMID 35586047, 2022). "So we conclude that SIK2 can improve the mitochondrial autophagy restriction which is induced by cerebral ischemia-reperfusion to promote the occurrence of energy metabolism through the mTOR pathway in rats." (PMID 35586047, 2022). "It is concluded that SIK2 can be used as a positive regulator of cerebral ischemia-reperfusion injury to reduce the brain tissue damage." (PMID 35586047, 2022). "The experiments we completed before have confirmed that SIK2 had impact on the brain tissue damage after cerebral ischemia-reperfusion in rats by regulating angiogenesis." (PMID 35586047, 2022). "We also found that Sik2−/− mice show resistance to brain ischemia; however, Sik2−/− mice are apparently normal in terms of body weight regulation." (PMID 22662228, 2012). "In addition, in mice with a disrupted Sik2 gene, downregulation of SIK2 expression confers resistance to oxidative stresses after brain ischemia and enhances melanogenesis in melanocytes after ultraviolet irradiation." (PMID 22662228, 2012). "In addition to these roles, we also found that TORC1 is essential for neuronal survival after brain ischemia, which is evident in Sik2−/− mice." (PMID 22022544, 2011). "In this study, we proved that SIK2 could promote the level of energy metabolism and mitochondrial autophagy-related proteins after cerebral ischemia-reperfusion in rats, and increase the level of ATP in brain tissue, which indicates that it plays a protective role in brain injury." (PMID 35586047, 2022). "In this study, we confirmed that SIK2 could play a similar role to AMPK in the mTOR pathway, which promoted the phosphorylation expression of mTORC1 and the energy metabolism, induced the occurrence of mitochondrial autophagy, and improved the cerebral ischemia-reperfusion injury." (PMID 35586047, 2022).
diabetes (4 papers, 2017 to 2025). "It was also proposed that SIK2 is involved in the β-cell compensation during hyperglycemia and loss of SIK2 contributes to β-cell failure and diabetes." (PMID 39081779, 2024). "Although SIKs (SIK1, SIK2, and SIK3) have shown critical roles in multiple contexts of physiology and participate in distinct human diseases, such as cancer, diabetes, colitis, and sepsis, the role of SIKs in psoriasis is poorly understood." (PMID 39959414, 2025).
Hyperglycemia (4 papers, 2016 to 2024). An increased concentration of glucose in the blood. "Inducible, post-natal SIK2/3 gene deletion caused dramatic bone anabolism without hyperglycemia or BUN elevation, indicating that these side effects were due to inhibition of SIK1 or other targets of YKL-05–099." (PMID 34160349, 2021). "Second, YKL-05–099 caused mild hyperglycemia and increased BUN, changes not observed following Sik2/3 deletion." (PMID 34160349, 2021). "SIK2 functions as a negative modulator of the insulin-dependent survival pathway and contributes to hyperglycemia-induced cell death of Muller glia." (PMID 27504893, 2016).
prostate carcinoma (4 papers, 2020 to 2025). A carcinoma that arises from epithelial cells of the prostate gland. "Moreover, overexpression of SIK2 has been reported in different types of cancer, whereas inhibition of SIK2 was shown to suppress proliferation of ovarian and prostate cancer cells." (PMID 34058059, 2022). "However, CD10, KHDRBS3, PCLAF, PSMA, SIK2 and GDF15 were differentially expressed with prostate cancer progression." (PMID 39578642, 2025).
colitis (3 papers, 2023 to 2026). Inflammation of the colon. "Preclinical studies in mouse models of colitis, psoriasis, and arthritis demonstrated that SIK2/SIK3 inhibition reduced inflammatory activity and promoted immunoregulatory and tolerogenic-associated pathways." (PMID 41657312, 2026).
fibrosis (3 papers, 2022 to 2025). the formation of excess fibrous connective tissue in an organ or tissue in a reparative or reactive process. "As SIK2 did not appear to affect the initial inflammatory phase of bleomycin-induced lung inflammation, we next examined its potential effects on fibrosis using a 22 day model." (PMID 36309093, 2022).
glioma (3 papers, 2015 to 2025). A benign or malignant brain and spinal cord tumor that arises from glial cells (astrocytes, oligodendrocytes, ependymal cells). "Mechanistically, B55γ stabilizes SIK2 through direct interaction, and this B55γ–SIK2 axis is essential for inhibiting S6K phosphorylation in glioma cells." (PMID 41146310, 2025). "Furthermore, from proteomic analysis, we found B55gamma binds with SIK2 and increases SIK2 stability in Glioma cells which is required in the B55gamma-mediated suppression of the phosphorylation of S6K." (PMID 25792973, 2015).
liver cancer (3 papers, 2017 to 2024). An epithelial or non-epithelial malignant neoplasm that arises from the liver. "Recently, SIK2 was associated with better survival in renal and liver cancer patients." (PMID 29774109, 2018). "Previous studies have suggested that SIK2 is an important upstream regulator of carbohydrate response element-binding protein promoting the progression of liver cancer." (PMID 39063214, 2024). "In contrast to its tumor promoting roles, SIK2 was also suggested to suppress metastasis and contributed to patient survival in renal and liver cancers." (PMID 29774109, 2018). "Using The Cancer Genome Atlas datasets to re-analyze the effect of some previously reported metastatic genes-e.g., JAM2, PPARGC1A, SIK2, and TRAF6-on overall survival of patients with renal and liver cancers, we found that these genes are actually protective factors for patients with cancer." (PMID 28372569, 2017).
pancreatic cancer (3 papers, 2024 to 2025). "SIK2 is overexpressed in ovarian, breast, prostate, and pancreatic cancers and contributes to tumor progression." (PMID 40612876, 2025). "Protein database analysis suggests that FBXW7 also inhibits the downstream TORC2/AKT signaling pathway by degrading salt-inducible kinase 2 (SIK2), thereby reducing pancreatic cancer cell proliferation." (PMID 39749199, 2024). "It has also been shown that in pancreatic cancer FBXW7 could interfere with AKT signaling activity by targeting SIK2 degradation." (PMID 40083925, 2025). "Firstly, we looked into how sensitive breast and pancreatic cancer cells were to SIC-19, a small molecule inhibitor of SIK2, when used as a monotherapy target." (PMID 40612876, 2025). "We then selected the TNBC cell lines MDA-MB-231 and HCC1806 as well as the pancreatic cancer cell lines BXPC3 and PANC1, which have high expression of SIK2 and complete homologous recombination repair function, for experiments." (PMID 40612876, 2025).
psoriasis (3 papers, 2021 to 2026). An autoimmune condition characterized by red, well-delineated plaques with silvery scales that are usually on the extensor surfaces and scalp. "Our data showed that SIK1 was upregulated in IMQ-induced psoriasis, but SIK2 and SIK3 showed similar expression compared with control mice." (PMID 39959414, 2025). "Several psoriasis-related genes were among the associated genes of hsa_skin_088763, including GATA6, SIK2, IL17RD, EGR3, FAS, LRIG1, and PPARGC1A." (PMID 34068434, 2021). "LRIG1 negatively regulates growth factor signaling to regulate epidermal stem cell quiescence; SIK2 modulates cytokine responses during innate immune activation; FAS signaling is essential for inducing key inflammatory cytokines in psoriasis." (PMID 34068434, 2021).
acute myeloid leukemia (2 papers, 2022 to 2024). Acute myeloid leukemia (AML) is a group of neoplasms arising from precursor cells committed to the myeloid cell-line differentiation. "Since FA patients display a high risk of childhood acute myeloid leukemia (AML), we stably knocked down FANCA in the AML cell line THP‐1 to assess sensitivity to SIK2 inhibition in a relevant cancer type." (PMID 34058059, 2022).
cardiac hypertrophy (2 papers, 2014 to 2024). "In contrast, SIK2 activation has been implicated in cardiac hypertrophy." (PMID 39081779, 2024). "SIK1 and SIK2 play distinct roles in mediating the HS-induced high BP and cardiac hypertrophy in mouse models." (PMID 39081779, 2024). "Further evidence also supports a pathological role for SIK2 in cardiac hypertrophy." (PMID 39081779, 2024). "Furthermore, the mRNA expression of SIK2, α-adducin, and genes related to cardiac hypertrophy are positively correlated in human cardiac biopsies." (PMID 39081779, 2024). "In addition, the mRNA expression of SIK2, α-adducin, and genes related to cardiac hypertrophy are also positively correlated in human cardiac biopsies." (PMID 39081779, 2024). "Moreover, the mRNA expression levels of SIK2, α-adducin, and several markers of cardiac hypertrophy were positively correlated in tissue biopsies obtained from human hearts." (PMID 24752134, 2014). "At the molecular level, the mRNA expression of markers of cardiac hypertrophy was significantly higher in the LV from sik2+/+ mice drinking 1% saline vs. normal salt (β-MHC = A.U.: 0.53±0.05 vs. 1.23±0.26, p = 0.025; MEF2C = A.U.: 0.38±0.02 vs. 0.62±0.01, p = 0.045), but not in sik2−/− mice." (PMID 24752134, 2014). "Instead, combined Sik1/2 deletion leads to higher BP but does not alter LVH on chronic HS intake, suggesting that SIK1 is required for maintaining normal BP while SIK2 is required for HS-induced cardiac hypertrophy independent of high BP." (PMID 39081779, 2024). "SIK2 deletion prevents HS-induced cardiac hypertrophy independent of high BP." (PMID 39081779, 2024).
cervical cancer (2 papers, 2020 to 2022). A primary or metastatic malignant neoplasm involving the cervix. "In our research, we verified that miR-526b directly targets the SIK2 to reduce the protein levels of SIK2 in cervical cancer." (PMID 33344445, 2020). "CircAMOTL1 expression was inversely correlated with miR-526b and positively correlated with SIK2 mRNA in cervical cancer tissues." (PMID 33344445, 2020). "Further experiments have been manifested that knockdown of SIK2 dramatically reversed the promotion of SIK2 expression induced by overexpressing circAMOTL1 in cervical carcinoma cells." (PMID 33344445, 2020). "Knockdown of circAMOTL1 restrained SIK2 expression by IHC experiments of cervical carcinoma cells in vivo." (PMID 33344445, 2020). "Overexpression miR-526b reduced SIK2 expression and miR-526b inhibition upregulated SIK2 expression in cervical carcinoma cells." (PMID 33344445, 2020). "Silencing of SIK2 reversed malignant cervical carcinomas cells phenotypes promotion of overexpression circAMOTL1." (PMID 33344445, 2020). "CircAMOTL1-miR-526b-SIK2 axis referred to the malignant progression and development of cervical carcinomas." (PMID 33344445, 2020). "CircAMOTL1 promotes tumor progression in cervical cancer by sponging miR-526b to upregulate SIK2." (PMID 33344445, 2020). "And SIK2 knockdown could obviously reverse cervical carcinoma cells migration and invasion induced by overexpression circAMOTL1." (PMID 33344445, 2020). "And SIK2 knockdown could obviously reverse cervical carcinoma cells migration induced by overexpression circAMOTL1." (PMID 33344445, 2020). "In conclusion, the experiments manifested that circAMOTL1-miR-526b-SIK2 axis could play some significant roles in the progression and development of cervical carcinomas." (PMID 33344445, 2020). "CircAMOTL1 facilitated cervical carcinoma cells tumorigenicity via upregulating SIK2 expression." (PMID 33344445, 2020). "Moreover, knockdown of SIK2 obviously reversed cervical carcinoma cells proliferation promotion induced by overexpression circAMOTL1." (PMID 33344445, 2020). "CircAMOTL1 could closely regulate SIK2 expression via sponging miR-526b in cervical carcinoma cells." (PMID 33344445, 2020). "Our study manifested that the circAMOTL1 expression was closely related to SIK2 expression and downregulated circAMOTL1 could reduce SIK2 expression in cervical carcinomas cells." (PMID 33344445, 2020). "CircAMOTL1 could accelerate malignant cervical carcinoma cells phenotypes via SIK2-dependent manner." (PMID 33344445, 2020). "Meanwhile, SIK2 knockdown could notably reverse cervical carcinoma cells apoptosis suppression induced by overexpression circAMOTL1." (PMID 33344445, 2020). "The experiments have been manifested that circAMOTL1 could sponge miR-526b to closely regulate SIK2 expression and subsequently accelerate the malignant cervical carcinomas cells’ phenotypes and EMT, and therefore could act as a carcinogene in the cervical carcinoma mechanism." (PMID 33344445, 2020). "Upregulated SIK2 protein could facilitate transcription and translation of proteins operating through indispensably abnormal protein signaling pathways, and subsequently could accelerate malignant cervical carcinoma cells phenotypes." (PMID 33344445, 2020). "CircAMOTL1 acts as a microRNA (miRNA) sponge that actively regulates the expression of salt-inducible kinase 2 (SIK2) to sponge miR-526b and subsequently increases malignant phenotypes of cervical carcinomas cells." (PMID 33344445, 2020). "Knockdown of circAMOTL1 decreased SIK2, p-AKT, N-Cadherin, Vimentin, Slug, Snail, Twist, and upregulated E-Cadherin expression in cervical carcinoma cells." (PMID 33344445, 2020). "Knockdown of circAMOTL1 could reduce SIK2, p-AKT, N-Cadherin, Vimentin, and upregulated E-Cadherin expression of cervical carcinoma cells in vivo." (PMID 33344445, 2020).
epilepsy (2 papers, 2022 to 2023). A brain disorder characterized by episodes of abnormally increased neuronal discharge resulting in transient episodes of sensory or motor neurological dysfunction, or psychic dysfunction. "In this study, we used the recently developed inhibitor YKL‐06‐061, which has a high affinity for SIK1 and 3, but to a lesser extent for SIK2, and tested its effects on seizure development in rodent epilepsy models." (PMID 37919236, 2023). "Pin1 also regulates Ca2+ influx by binding to salt-induced kinase 2 (SIK2) and decreasing the expression of p35, a negative regulator of Ca2+ influx, yet the effect is induced by high glucose, which is not the same as the microenvironment of epilepsy." (PMID 36304997, 2022).